RNU6-1241P (RNA, U6 small nuclear 1241, pseudogene)
Gene: Small nuclear RNA gene on chromosome 16 (27,998,295 to 27,998,401, reverse strand). Ensembl gene ENSG00000207266.
Homologues: Orthologues: chimpanzee U6 (97% identical), macaque U6 (89% identical), mouse Gm25633 (87% identical), rabbit U6 (84% identical), guinea pig U6 (81% identical), dog U6 (69% identical). Paralogues in human: RNU6-945P (89% identical), RNU6-1181P (88% identical), RNU6-90P (87% identical), RNU6-968P (87% identical), RNU6-1145P (86% identical), RNU6-12P (86% identical), RNU6-13P (86% identical), RNU6-16P (86% identical), RNU6-32P (86% identical), RNU6-36P (86% identical), RNU6-393P (86% identical), RNU6-41P (86% identical), and 1290 more.